MTOR (mechanistic target of rapamycin kinase)
Diseases named in the same sentence as MTOR in open-access papers (continued):
Sharing a sentence is not in itself a finding about the gene and the disease.
mastitis (12 papers, 2021 to 2026). Inflammation of breast tissue during lactation or postpartum due to an obstructed duct or infection. "In conclusion, SeD-EV caused oxidative stress, thus triggering apoptosis and inflammation through endoplasmic reticulum stress and the PI3K-Akt-mTOR signaling pathway, which contributed to explaining the mechanism of Se deficiency causing mastitis." (PMID 38136197, 2023). "Extracellular vesicles derived from selenium-deficient bMECs induced oxidative stress, provoking apoptosis and inflammation via endoplasmic reticulum stress and PI3K/Akt/mTOR signaling pathway, contributing to explain susceptibility to mastitis due to selenium deficiency." (PMID 39456758, 2024). "This intervention not only reactivates AKT1 expression and its downstream mTOR pathway, but also restores milk protein synthesis, directly alleviating mastitis symptoms." (PMID 40711322, 2025). "However, exosome secretion significantly promoted inflammatory cell infiltration in the progression of plasma cell mastitis via the PI3K/Akt/mTOR signaling pathway." (PMID 36611779, 2023). "Hierarchical level two showed that 18 signaling pathways are involved in the regulation of mastitis, including MAPK, Ras, cGMP-PKG, NF-κb, phosphatidylinositol, and mTOR, wnt, and TNF pathways." (PMID 36204322, 2022).
periodontitis (12 papers, 2021 to 2026). An acute or chronic inflammatory process that affects the tissues that surround and support the teeth. "Single‐cell RNA sequencing revealed gingival fibroblasts (GFs) as the primary FAP and OLN source, with periodontitis‐associated GFs showing increased reactive oxygen species, cellular senescence, and mTOR pathway activation." (PMID 39716898, 2025). "Periodontitis causes excessive activation of the mTOR signaling pathway in fibroblasts, accelerating cellular senescence." (PMID 39716898, 2025). "Metformin also alleviates HMGB1-mediated oxidative stress through the mTOR pathway in experimental periodontitis." (PMID 40385486, 2025). "Overall, senescent gingival fibroblasts disrupt the FAP/OLN balance via the mTOR signaling pathway, playing a critical role in periodontitis progression." (PMID 39716898, 2025). "Quercetin has a potential protective effect against chronic inflammation-related periodontitis by suppressing the Akt/AMPK/mTOR pathway." (PMID 38178140, 2024). "Ellagic acid present in pomegranates induces autophagy in periodontitis via controlling mTOR signaling." (PMID 39595208, 2024). "Luteolin, a compound present in many vegetables and fruits, triggers autophagy in periodontitis by suppressing the mTOR pathway via AMPK stimulation." (PMID 39595208, 2024). "Berberine derived from the Berberis plant, stimulates autophagy in periodontitis by suppressing mTOR signaling, resulting in the elimination of germs and a decrease in inflammation of the gums." (PMID 39595208, 2024). "The exact roles of mTOR-autophagy cascades on the initiation and progression of periodontitis still need to be evaluated through further studies." (PMID 35222410, 2022). "Inflammation enhanced autophagy levels of HPDLFs in periodontitis, which accordingly regulated mTOR and ERK, the two important signaling pathways." (PMID 33270996, 2021). "Therefore, the findings of this study provide an experimental basis for the prevention and treatment of AGE-aggravated periodontitis by targeting inflammaging through the RAGE/AKT/mTOR pathway and glycolysis." (PMID 40839341, 2025). "Therefore, senescent fibroblasts drive the FAP/OLN imbalance through mTOR activation, contributing to periodontitis progression." (PMID 39716898, 2025). "Their findings unveiled reduced bone resorption and diminished pro-inflammatory cytokine levels in C57bl/6-10 mice compared to Balb/c mice, accompanied by heightened activation of the PI3K/Akt pathway and attenuated activation of the mTOR pathway in a ligature-induced periodontitis model." (PMID 39086605, 2024). "There are medicines targeting the mTOR-signaling which have already been used in clinical for treating cancers and may be beneficial for the treatment of periodontitis in the future." (PMID 35222410, 2022). "However, whether mTOR signaling is involved in periodontitis through regulating CD4+ T cell differentiation remains unknown." (PMID 35222410, 2022). "Since different mTOR complexes play distinctive roles on CD4+ T cell fate determination, explicit deletion or activation of mTORC1 and mTORC2 has been recommended to explore their exact roles on periodontitis." (PMID 35222410, 2022). "As autophagy is inhibited by mTORC1, the negative effect of mTOR signaling on periodontitis may go through autophagic regulation." (PMID 35222410, 2022). "The p‐Akt/Akt and p‐mTOR/mTOR ratios were lower in groups subjected to CMS, with or without previous periodontitis, compared with the control group (P‐CMS‐)." (PMID 41326981, 2025).
progeria (12 papers, 2012 to 2025). "Rapamycin has been shown to remove progeria via improved autophagy and reduce senescence in patients with Hutchinson-Gilford progeria syndrome, as inhibition of the mTOR pathway can lengthen life expectancy in mice." (PMID 38355681, 2024). "Inhibitors of the mechanistic target of rapamycin (mTOR) have also shown some promise in vitro in treating progeria cells, thus we also examined the potential benefits of late-term daily injections of rapamycin." (PMID 36930696, 2023). "Rapamycin via mTOR/mTORC1 inhibition improves immune function in the elderly, and also prevents aging of skeletal muscle which is relevant in light of reports of progeria in DM1." (PMID 35328504, 2022). "In particular, MDSPCs isolated from prelamin A-expressing progeria mice exhibit increased mTOR signaling." (PMID 32046343, 2020). "Classical pathways associated with metabolic alterations in other diseases are beginning to be interrogated in progeria, including mTOR, AMPK, Sirtuins, mitochondrial function, and most recently ATM signaling." (PMID 32046343, 2020). "Recent work has revealed that rapamycin, an mTOR (mammalian target of rapamycin) inhibitor, significantly reduces the phenotypic hallmarks of progeria in HGPS cells by down-regulating progerin." (PMID 22354768, 2012). "In this regard, some compounds with the ability to induce progeria degradation through autophagy activation have been previously identified, including rapamycin (inhibitor of mTOR pathway), MG132 (proteasome inhibitor), sulforaphane (antioxidant compound) and neuropeptide Y." (PMID 39871520, 2025). "Finally, we examined possible benefits afforded by a combination therapy, daily intraperitoneal injections of the mTOR inhibitor rapamycin from P100 to P168 in progeria mice that received lonafarnib daily from P21 to P168 via the soft chow." (PMID 36930696, 2023). "Thus, inhibition of the mTOR pathway is a strategy to decelerate aging in progerias." (PMID 24799429, 2014). "Mechanistically, genetic studies have pointed to the involvement of several key events, notably DNA damage, particularly in the progeria/progeroid syndromes and activities of the insulin/IGF1/mTOR/FOXO pathway in longevity." (PMID 35531366, 2022). "However, there is no consensus in the field yet about the activation of mTOR signaling in progeria cells of different origin and about the net beneficial effects of rapamycin treatment in different mouse models of HGPS." (PMID 32046343, 2020).
tongue squamous cell carcinoma (12 papers, 2017 to 2024). A squamous cell carcinoma that arises from the tongue. "In conclusion, p-mTOR overexpression was independently associated with poor prognosis in patients with tongue SCC." (PMID 28811537, 2017). "In conclusion, p-mTOR overexpression was independently associated with poor prognosis of patients with tongue SCC." (PMID 28811537, 2017). "In 4-NQO-induced tongue cancer murine model, mTOR inhibitors significantly decreased the incidence of tongue SCC." (PMID 28811537, 2017). "In the present study, immunohistochemistry was performed to evaluate the expression of phosphorylated mTOR (p-mTOR) in 160 surgically resected tongue SCC, and correlated with survival." (PMID 28811537, 2017). "In addition, CAPS in combination with cisplatin suppresses transforming growth factor-β1-induced epithelial–mesenchymal transition (EMT) through the activation of claudin 1 and inhibition of the PI3K/AKT/mTOR pathway in squamous cell carcinoma of the tongue." (PMID 39519591, 2024). "It was reported that 53% of tongue squamous cell carcinoma had p-MTOR overexpression." (PMID 34335829, 2021). "In vitro and vivo, mTOR inhibition showed the promising activity in tongue SCC." (PMID 28811537, 2017). "Altogether, these results suggest that silencing mTOR expression/activity may provide a potential strategy for the treatment of tongue squamous cell carcinoma." (PMID 28811537, 2017). "Our results suggest that inhibition of mTOR signaling pathway may be a novel therapeutic target for the treatment of tongue SCC." (PMID 28811537, 2017). "Our results suggest that inhibition of mTOR signaling pathway may be a novel therapeutic target for tongue SCC." (PMID 28811537, 2017). "Therefore, we conducted the present study to evaluate the significance of mTOR activation on the prognosis of tongue SCC." (PMID 28811537, 2017). "However, the significance of mTOR on the prognosis of tongue SCC remains largely undefined." (PMID 28811537, 2017). "In tongue squamous cell carcinoma (TSCC) cells, SNHG26 directly binds to the PGK1 protein, inhibiting its ubiquitination and activating the Akt/mTOR signalling pathway." (PMID 37723547, 2023).
adenomyosis (11 papers, 2017 to 2026). The growth of endometrial tissue inside the muscular wall of the uterine corpus. "Aberrant mTOR pathway activation is also reflected in the abnormal expression of mTOR-associated eIFs in adenomyosis." (PMID 35408777, 2022). "This loss of rhythmic LC3A expression in adenomyosis patients was linked to a decrease in TSC2 expression, which in turn would inhibit autophagy through the activation of the mTOR signaling pathway." (PMID 39768424, 2024). "These insights underscore the potential of targeting the PI3K/AKT/mTOR signaling pathway to modulate the pathogenesis of adenomyosis, opening up novel avenues for both research and therapeutic intervention." (PMID 39595579, 2024). "This review summarizes the signaling pathways and targets associated with the pathogenesis of adenomyosis, including CXCL/CXCR, NLRP3, NF-κB, TGF-β/smad, VEGF, Hippo/YAP, PI3K/Akt/mTOR, JAK/STAT, and other relevant pathways." (PMID 39595579, 2024). "The endometria of patients with adenomyosis are under conditions of high oestrogen stimulation and progesterone resistance, which represses the local autophagy condition through the mammalian target of rapamycin (mTOR) pathway." (PMID 35761172, 2022). "Multiple studies have reported the involvement of upstream regulators of the mTOR pathway in the development of adenomyosis." (PMID 35408777, 2022). "Estrogen acts by stimulating the PI3K/AKT/mTOR pathway, which is known to be activated in adenomyosis, leading to endometrial epithelial cell invasion and migration." (PMID 35408777, 2022). "Overall, these results showed that chronic suppression of mTOR signaling inhibits age-related incidences of endometrial hyperplasia and adenomyosis in mice." (PMID 27980219, 2017). "Therefore, one therapeutic strategy for intervening in the development and progression of adenomyosis involves inhibiting the excessive activation of the PI3K/AKT/mTOR signaling pathway, thereby regulating the balance between proliferation and apoptosis." (PMID 39595579, 2024). "mTOR signaling may also be involved in the pathogenesis of adenomyosis by promoting epithelial to mesenchymal transition (EMT) of endometrial epithelial cells." (PMID 35408777, 2022). "Besides upstream effectors, downstream regulators of mTOR signaling seem to play a significant role in adenomyosis as well." (PMID 35408777, 2022). "Furthermore, mTOR signaling is dysregulated in adenomyosis due to the altered expression of non-coding RNAs." (PMID 35408777, 2022). "It follows that targeting the PI3K/AKT/mTOR pathway may be effective for adenomyosis treatment." (PMID 35408777, 2022). "DNA and protein synthesis in response to estrogen is mediated through mTOR signaling in human and mouse endometrial cells, suggesting that mTOR signaling may mediate unopposed estrogen signaling in endometrial diseases, such as endometrial hyperplasia/cancer and adenomyosis." (PMID 27980219, 2017). "Undoubtedly, the upstream and downstream molecules of the PI3K/AKT/mTOR, JAK/STAT, and Hippo signaling pathways are potential targets for adenomyosis treatment." (PMID 39595579, 2024). "In adenomyosis, the ncRNAs known to influence the disease progression via modulating the PI3K/AKT/mTOR pathway are microRNAs (miRNAs) and long non-coding RNAs (lncRNAs)." (PMID 35408777, 2022).
Anorexia (11 papers, 2012 to 2025). Lack of desire to eat (loss of appetite). "Among them, LAM patients taking mTOR inhibitors regularly had a lower risk of fatigue [OR: 0.18, 95% CI: (0.03, 0.95)], anorexia [OR: 0.30, 95% CI: (0.09, 0.96)], and ageusia [OR: 0.20, 95% CI: (0.06, 0.67)]." (PMID 38956624, 2024). "The hormone leptin increases hypothalamic mTOR activity and inhibition of mTOR signaling has been associated with anorexia." (PMID 23203037, 2012). "Given that E2- and PPT-induced anorexia in association to increased mTOR signaling in the ARC of OVX rats, we next aimed to investigate whether activation of this pathway impacted feeding in OVX rats." (PMID 29914932, 2018). "Multivariate analysis indicated that patients in the group regularly using mTOR inhibitors exhibited a lower incidence of fatigue, ageusia, and anorexia." (PMID 38956624, 2024). "Our results showed that phosphorylation of the ribosomal protein S6 level was significantly higher in the mandarin fish of Group B, suggesting that the anorexia was related to the activation of mTOR pathway." (PMID 32636801, 2020). "In the hypothalamus, leptin inhibits food intake through mTOR activation, and mTOR inhibition with rapamycin prevents leptin-induced anorexia." (PMID 22701480, 2012). "ICV administration of l-leucine, a potent activator of mTOR, reduces the levels of NPY in ARC, produces anorexia and causes weight loss, while l-valine, similar in structure but unable to activate mTOR, does not have such an effect." (PMID 29107294, 2017). "Initially, it was proposed that activation of mTOR signaling in the hypothalamus promoted anorexia; in fact it was demonstrated that short-term central administration of anorectic factors, such as leucine, leptin, CNTF, α-lipoic acid or BMP7 increase hypothalamic mTOR signaling." (PMID 23056530, 2012).
Immunodeficiency (11 papers, 2018 to 2025). Failure of the immune system to protect the body adequately from infection, due to the absence or insufficiency of some component process or substance. "Cd-induced inhibition of mTOR has been shown previously leading to autophagy, suggesting that autophagy plays an important role in Cd-induced immune deficiency." (PMID 31963425, 2020). "Indeed, several human PIDs that are associated with a hyperactivation of the PI3K/AKT/mTOR/S6K pathway have features of both immunodeficiency and immune dysregulation, suggesting a tight and dynamic modulation of the signaling cascade for optimal immune cell function." (PMID 29867948, 2018). "More specifically, we found replication for the majority of the top pathways: E2F targets, mTOR and MYC pathways identified in a large mega-analysis based on gene expression in blood, and immunodeficiency in a meta-analysis using multiple tissues." (PMID 31719968, 2019). "Consistent with what is observed in other PIRDs, unfortunately, mTOR inhibition did not prevent the progression of the immunodeficiency that ultimately generated the indication to HSCT." (PMID 35663969, 2022).
intrahepatic cholangiocarcinoma (11 papers, 2014 to 2025). A carcinoma that arises from the intrahepatic bile duct epithelium in any site of the intrahepatic biliary tree. "Studies shown that PI3K/AKT/mTOR/autophagic axis can promote intrahepatic cholangiocarcinoma progression and desensitizes cisplatin treatment." (PMID 40713706, 2025). "In intrahepatic cholangiocarcinoma Apatinib inhibits VEGFR2 mediated PI3K/AKT/mTOR signaling pathway which is a central regulator of cellular translation." (PMID 31570733, 2019). "IL-6 induced programmed death ligand 1 expression through the mTOR pathway in intrahepatic cholangiocarcinoma, suggesting that IL-6 antibodies may help to overcome resistance to immune checkpoint inhibitors in intrahepatic cholangiocarcinoma." (PMID 38689325, 2024). "Notably, recent study indicated that HAGLROS was highly expressed and decreasing HAGLROS can inactivate the mTOR axis and elevate autophagy through improving lipid metabolism reprogramming in intrahepatic cholangiocarcinoma." (PMID 35664787, 2022). "In our previous study, we revealed that the mTOR inhibitor MLN0128 could suppress intrahepatic cholangiocarcinoma (ICC) development in AKT/YAP mice mainly through the induction of strong apoptosis." (PMID 31277283, 2019).
iron deficiency (11 papers, 2012 to 2025). "On contrary, low-grade inflammation and the use of mammalian target of rapamycin (mTOR) inhibitors promote the upregulation of hepcidin, leading to reduced iron availability (functional iron deficiency) for erythropoiesis." (PMID 37415623, 2023). "The authors conclude that the mTOR protein seems to be regulated by iron, as iron deficiency resulted in a marked reduction in mTORC1 signaling in RBCs in vitro and in vivo." (PMID 34202704, 2021). "If AMPKα1 proportionally increases with iron deficiency, the mTOR pathway would be further inhibited in ID animals than in C animals, causing increased inhibition of protein synthesis, and therefore decreased growth." (PMID 23171474, 2012). "Magnesium deficiency was also shown to decrease mTOR phosphorylation at serine 2448." (PMID 33923895, 2021). "Moreover, iron deficiency can reduce mTOR activity in hippocampus via REDD1, a signaling molecule that can be activated by reactive oxygen species." (PMID 28567002, 2017). "To determine whether mTOR modulates bulk translation during iron deficiency, we determined the phosphorylation state of the eIF4E-binding protein (4EBP1), which decreases under stress conditions due to a drop in mTOR activity, resulting in recruitment of eIF4E and translation impairment." (PMID 38605136, 2024). "This may affect the mTOR (Mammalian Target of Rapamycin) pathway and BDNF (brain-derived neurotrophic factor) expression, potentially causing long-term brain dysfunction that persists even after iron deficiency is corrected after birth." (PMID 40429475, 2025). "Models of non-anemic iron deficiency have shown an overall upregulation of mTOR signaling and both positive (AKT) and negative (AMPK) regulators of mTOR." (PMID 40863165, 2025).